CREBBP (CREB binding lysine acetyltransferase )
Diseases named in the same sentence as CREBBP in open-access papers (continued):
Sharing a sentence is not in itself a finding about the gene and the disease.
cancer (169 papers, 2006 to 2026). A tumor composed of atypical neoplastic, often pleomorphic cells that invade other tissues. "In the pan-cancer cohort, the presence of mutations in at least one of these genes was associated with a two-fold improvement in survival compared with WT CREBBP/EP300 tumors." (PMID 41301688, 2025). "In the pan-cancer cohort, patients with mutations in the target genes exhibited a median overall survival of 34 months, twice that observed in the WT CREBBP/EP300 group (17 months; log-rank p-value = 2.4 × 10−3)." (PMID 41301688, 2025). "In the present study, we show that simultaneous inhibition of two genes (CREBBP + EP300) causes synthetic lethality in cancers with a LOF mutation in another gene (i.e., SMARCB1)." (PMID 38839769, 2024). "Exemplary cases include ncORFs in the cancer hallmark genes CREBBP, CRTC1, CSF3R, FGFR2, IKZF1 and MAP2K2 with peptide support in all but two of the analyzed cancer types." (PMID 37275273, 2023). "The human acetyltransferase paralogs EP300 and CREBBP are master regulators of lysine acetylation whose activity has been implicated in various cancers." (PMID 37292747, 2023). "The mutational analysis highlighted the likely importance of NRAS, KRAS, JAK2, and CREBBP in pediatric cancer development because these genes are the most commonly mutated genes in pediatric cancer patients." (PMID 36497424, 2022). "Genes of interest from the selected cancer‐related gene set, restricted to gene mutations occurring in >3 patients, revealed mutations in several genes previously reported in FL (e.g., CREBBP, BCL2, KMT2D)." (PMID 34791836, 2022). "A recent population-based study of a Dutch RTS cohort evaluated characteristics of benign and malignant tumors in patients with RTS with mutations in CREBBP (70%) and EP300 (5–10%)." (PMID 31924266, 2020). "CREBBP polymorphisms were significantly more frequent in iCCA patients (50.0%) than in OV-infected individuals (30.0%) and healthy controls (30.8%) (P = 0.003), with homozygous mutations conferring the highest cancer risk (OR = 6.43, 95% CI: 1.70-24.31)." (PMID 42102112, 2026). "Finally, the independent prognostic impact of CREBBP mutations was further evaluated by comparing the CREBBP group (n = 84) against all other patients in the pan-cancer cohort (WT CREBBP)." (PMID 41301688, 2025). "Pilot study indicated that CREBBP mutation may be involved in mutation profile that fitted Big Bang cancer evolution model." (PMID 34195081, 2021). "We identified that CREBBP had relatively high mutation frequencies across cancer types." (PMID 34136387, 2021). "In cancer, CREBBP/EP300 is targeted by both mutations and structural alterations." (PMID 32493417, 2020). "Therefore, it is possible that p300 inhibitors exhibit a synthetic lethal anticancer effect in CREBBP-deficient cancer cells by inhibiting the expression of MYC." (PMID 31590683, 2019). "Loss-of-function mutations of the CREBBP gene are very common in a variety of cancers." (PMID 31590683, 2019). "This phenomenon provides a potential treatment for CREBBP-deficient cancers." (PMID 31590683, 2019). "CREBBP has been implicated in the carcinogenesis of several cancers." (PMID 25915404, 2015). "In addition, the activity of CREBBP/EP300 has been implicated in several types of human cancers." (PMID 40338073, 2025). "Likewise, this strategy could be extensible to NSCLC (8% of patients have a CREBBP mutated background) and other cancer types." (PMID 32645997, 2020). "Our results match patterns observed in large-scale drug-sensitivity studies, which have found many cancer cell lines to be insensitive to CREBBP/EP300 inhibitors." (PMID 40239999, 2025). "The cancer-associated genes PTEN (7%), KMT2C (7%), KMT2D (7%), RB1 (6%), and CREBBP (4%), were again among the 15 most frequently mutated and at similar frequencies as observed in CALGB 40603." (PMID 40057511, 2025). "The overall rarity of CREBBP and EP300 mutations, however, restricts interpretation for individual cancer types." (PMID 41301688, 2025).
cancer (continued). "The results revealed that the expression levels of EP300 and CREBBP (red bar) were greater in LAML than in other cancer types." (PMID 39885312, 2025). "Other notable mutated cancer-related genes include PIK3CA (7%), CREBBP (6%), KMT2C (6%), KMT2D (6%), RB1 (5%), PTEN (5%), and FAT1 (5%), all of which are reported as “Tier 1” cancer-related gene mutations in the COSMIC Cancer Gene Census21." (PMID 40057511, 2025). "The gene CREBBP was significantly upregulated in stage IVA and stage IVB patients, and the CREBBP gene plays a multifaceted role in cancer development and progression." (PMID 38539520, 2024). "This underscores the broader potential of EP300/CREBBP inhibition in steroid receptor-driven cancers, with FOXA1 signaling occupying a central role in these effects." (PMID 38564048, 2024). "We identified relationships between RBPs and various cancer types, including alterations in CREBBP and MBNL2 in adenocarcinomas of the lung, liver, prostate, rectum, stomach, and colon." (PMID 39595158, 2024). "EP300 and its homologue CREBBP encode highly related acetyltransferases that act as transcriptional coactivators in multiple signaling pathways, suggesting the potential involvement of EP300/CREBBP in cancers." (PMID 38693103, 2024). "The CREBBP BRD mutation disrupts its interaction with ASF1 causing Rubinstein-Taybi syndrome, and patients are prone to develop cancer." (PMID 36831561, 2023). "Aberrant expression of CREBBP/EP300 causes Rubinstein–Taybi syndrome and multiple hematologic malignancies by losing their activity." (PMID 36831561, 2023). "The mutational analysis determined that genes previously identified in cancers were most commonly observed in the profiled patients with mutations in NRAS, KRAS, JAK2, and CREBBP." (PMID 36497424, 2022). "Mutations in PTPRD, CREBBP, BRAF, NOTCH3, TERT, and SETD2, which are involved in various aspects of immune regulation, were reported as potential biomarkers in cancer patients after immunotherapy with improved survival." (PMID 36092890, 2022). "We find that known cancer driver genes such as CDKN2A and CREBBP are mutated in age-associated frequencies, and these alter the transcriptome and predict for clinical outcomes." (PMID 35017538, 2022). "Genetic variants of unclear significance were however detected in genes such as CDH1, DICER1, MEN1, RET, CREBBP, RAD51C, or SOS1, which are linked to autosomal dominant predisposition to cancer." (PMID 35250968, 2022). "The top four mutated genes in pediatric cancers were NRAS (1.8%), KRAS (0.9%), JAK2 (0.3%), and CREBBP (0.3%), highlighting that these genes should be analyzed further to assess the clinical significance of these mutations." (PMID 36497424, 2022). "Inhibition of p300 activity exhibits synthetic lethal effects on tumors deficient of CREBBP due to MYC downregulation, highlighting a critical role of having at least one functional paralog of these two proteins for cancer cell survival." (PMID 34201346, 2021). "Among eight HAMPs with M-scores > 0.4, EP300, PBRM1, and CREBBP had the largest overall M-scores across the 33 cancer types." (PMID 30760718, 2019). "For example, CREBBP and EP300 were widely mutated across multiple cancer types at relatively low frequencies; most of these mutations were heterozygous missense mutations." (PMID 30760718, 2019).
cancer (continued). "Our results indicate that ACTA2 is activated by the CREBBP-induced acetylation, which can potentially promote the invasive ability of cancer cells by the activation of cell migration in early stage LSCC." (PMID 31217907, 2019). "CREBBP and EP300 appeared to be widely mutated in multiple cancer types at a low to modest frequency (0.2–13.5% and 0.2–14.8%, respectively) and PBRM1 was highly mutated in KIRC (40.1%)." (PMID 30760718, 2019). "Our data shows that inhibition of CREBBP/EP300 bromodomains can interfere with oncogene-driven transcriptional programs in cancer cells and consequently hold therapeutic potential." (PMID 29884215, 2018). "Using network-based meta-analysis, we identified HDAC1 of the cell cycle pathway as the prominent hub gene in Cancer versus Normalcy and CIN versus Normalcy groups, while CREBBP was the prominent hub gene, among others, in Cancer versus CIN group." (PMID 29312619, 2017). "Four genes (AKAP9, ATM, CREBBP, and NF1) were mutated in only one subject but were reported on the Cancer Gene Census list, and the mutations were predicted to be detrimental by SIFT." (PMID 27689332, 2016). "CREB is a generic transcriptional activator that is involved in a plethora of developmental processes as well as cancer, and it functions by recruiting CREB-binding protein (CBP or CREBBP), which possesses HAT activity." (PMID 26733796, 2015). "Both CREBBP and EP300 have long been linked to cancer, though the specific roles they play have been harder to elucidate." (PMID 24622842, 2014). "By temporally dissecting mutations, we emphasized the significance of two cancer pathways, RTK-RAS and histone modification (especially KMT2D, KDM6 A and CREBBP), in the initiation of NMIBC due to the high enrichment in early mutations and high early selection preference, respectively." (PMID 40247187, 2025). "Interestingly, the post-translational regulation of HSD17B4 stability through acetylation at lysine 669—modulated by sirtuin 3 (SIRT3) and CREB-binding protein (CREBBP) —provides a potential mechanism for fine-tuning HSD17B4 activity in the context of cancer." (PMID 40647540, 2025). "Clinically, the expression of CREBBP was remarkably enhanced in various cancer tissues, especially in HCC, compared with that in normal tissues (P < 0.001) and resulted in lower OS (P = 0.009), PFI (P = 0.00082) and disease-free-interval (DFI; P = 0.0048) in HCC." (PMID 38493218, 2024). "Therefore, in this study, we focused on the paralog pair CREBBP and EP300 as a synthetic lethal target for SMARCB1-deficient cancers." (PMID 38839769, 2024). "In addition to the clinical non-CREBBP/EP300 inhibitors (tucidinostat and PRI-724), two targeted inhibitors of CREBBP/EP300 are currently in clinical trials in cancer patients." (PMID 36831561, 2023). "Eight targets (EP300, CASP3, CASP8, CHEK2, CREBBP, NOTCH1, PPARG, and TGFBR2) were TSGs (gray text), suggesting that antagonizing these molecules might increase the susceptibility to cancer in healthy individuals." (PMID 37888486, 2023). "Interestingly, the authors reported that the knockout of the cancer driver gene CREBBP exerts a positive growth impact on a 3D model but a negative growth effect in a 2D cancer cell line." (PMID 35449581, 2022). "CREBBP expression abnormalities have been found in patients with lung and prostate cancer." (PMID 36114448, 2022). "Recent cancer genome sequencing studies revealed mutations in many epigenetic modifiers that are associated with various cancers, such as DNMT3A in acute myeloid leukemia, IDH1/2 in glioblastoma, CREBBP/EP300 in small-cell lung cancer and ARID1A in gastric cancer." (PMID 35973998, 2022). "Previous studies have shown that CREBBP plays a role in cancer progression." (PMID 36114448, 2022). "Moreover, CRC cells have particularly high mutation rates in CREBBP and EP300 genes when compared to other cancer cell types." (PMID 34258881, 2021).
cancer (continued). "Chromosome translocations of both EP300 and CREBBP in cancer have also been observed." (PMID 34201346, 2021). "Probes targeting EP300/CREBBP were designed as cancer therapeutics." (PMID 33575256, 2020). "Although EP300/CREBBP-inactivating mutations have been observed in some cancers, secondary gain-of-function mutations in EP300/CREBBP may further propel cancer development." (PMID 33117683, 2020). "Furthermore, the inhibition of histone acetyltransferase activity of CREBBP and/or p300 has been reported to inhibit cancer cell growth in vitro and in vivo in many human cancers." (PMID 32489318, 2020). "Given the increasing implication of this chromatin-modifying complex in cancer and its interaction with CREBBP/EP30052, the defects in PBRM1 and ARID1A/B may contribute to SCLC." (PMID 31827074, 2019). "Our results suggest that CREBBP/EP300 bromodomain inhibitors might be able to reduce the tumorigenesis of cancers governed by oncogenic transcription factors that depend on CREBBP/EP300 to stimulate transcription and therefore hold therapeutic potential." (PMID 29884215, 2018). "In the unclassified subgroup, apart from previously reported mutations in epigenetic regulators in multiple cancers, including KMT2C, KMT2D, KMT2B, PRDM2, NCOR2, KAT6B, and EP300, in this cohort, we also found new recurrent mutations in epigenetic regulators, including CREBBP and PRDM16." (PMID 30950204, 2019). "These approaches identified several oncogenes, including KRAS, CREBBP, PTEN, and BRCA2, as SDL genetic partners of EXT1, highlighting its potential clinical relevance in different cancers." (PMID 33962942, 2021). "Our data show that inhibition of CREBBP/EP300 bromodomains can interfere with transcriptional outputs driven by oncogenes, such as GATA1 and MYC that function as transcription factors in cancer cells." (PMID 29884215, 2018). "Interestingly this is the first report describing mosaicism for CREBBP deletions, indicating the contribution of mitotic errors to this rare syndrome, that might exploit the same breakpoints of the highly unstable region around intron 2 of CREBBP evidenced in cancer." (PMID 17052327, 2006). "It is noteworthy that many genes within these pathways (e.g., AKT2, AKT3, CREBBP, MAPK1, GNAS, RPTOR) are already known to play relevant roles in cancer cell growth and proliferation, which could provide a plausible biological basis for such a link." (PMID 41226303, 2025). "Furthermore, the dysfunction of p107, p130, PTEN, chromatin regulator CREBBP, and NOTCH receptors contributes to cancer progression." (PMID 40761498, 2025). "Moreover, the dysfunction of the RB family (p107, p130), tumor suppressor PTEN, chromatin regulator CREBBP, and NOTCH receptors are other factors contributing to cancer pathogenesis." (PMID 40755497, 2025).
cancer (continued). "Acute catalytic CREBBP/EP300 inhibition modulates transcription independently of DNA accessibility and selectively suppresses transcription of distinct oncogenic networks in different cancer types." (PMID 36831561, 2023). "In addition to direct inhibition of CREBBP/EP300, blocking the interaction of CREBBP/EP300 with other oncogenic molecules is also an important anti-cancer pathway." (PMID 36831561, 2023). "However, since the RIP-seq results were also validated with real-time RT-PCR, at least six genes related to “Pathways in cancer,” i.e., TGFB2, CREBBP, EP300, FOS, JUN, and MYC were certainly affected by the hnRNPM-AS1-S interaction." (PMID 37671887, 2023). "In SCLC, it can be observed that cancer gene alterations appear to be more frequent in women, the most consistent differences being observed in PTRD, CREBBP, GRM3, ATRX, NOTCH3, and PDE4DIP, while ATM appears to be altered in 5.26% of men, and no alterations were depicted in women." (PMID 35330454, 2022). "Unlike PD-L1 negative regulators (HDAC1, HDAC2, and HDAC3), the expression ranks of PD-L1 and its positive regulators (EP300, CREBBP, IRF-1, and BRD4) negatively correlated to Grade Group in another study, suggesting an increase of function during cancer progression." (PMID 34830196, 2021). "Nevertheless, it is not clear how the increase in the KAT activity of EP300 or CREBBP promotes malignant tumors." (PMID 33117683, 2020). "Finally, CREBBP (DC = 190, BC = 512,840.8) and CDK2 (DC = 170, BC = 409,517.7) were recorded as the most potential hub genes in Cancer versus CIN group, whereas HDAC1 was a relatively low connected gene in this group (DC = 18, BC = 30,041.4)." (PMID 29312619, 2017). "Thus, simultaneous suppression of CREBBP and EP300, but not that of either alone, causes synthetic lethality in SMARCA4/SMARCA2-deficient and SS18–SSX fusion cancers." (PMID 39625239, 2025). "Thus, simultaneous dual suppression of CREBBP and EP300, but not single suppression, causes synthetic lethality in SMARCB1-deficient cancers." (PMID 38839769, 2024). "Interestingly, alterations in CREBBP among pediatric patients with ALL who do not relapse are rare, but CREBBP mutations are common in childhood ALL cases that do relapse, highlighting the importance of further elucidating their role in pediatric cancers." (PMID 36497424, 2022). "It is likely that dual inactivation of CREBBP and EP300 in tumors is critical and non-compensable, leading to high hypermutation in cancer genomes." (PMID 41301688, 2025).